PON2 (paraoxonase 2)
Diseases named in the same sentence as PON2 in open-access papers (continued):
Sharing a sentence is not in itself a finding about the gene and the disease.
lung adenocarcinoma (3 papers, 2016 to 2025). A carcinoma that arises from the lung and is characterized by the presence of malignant glandular epithelial cells. "In lung adenocarcinoma cells, loss of PON2 led to elevated ROS levels and mitochondrial depolarisation, resulting in increased apoptotic susceptibility." (PMID 40794328, 2025). "PON2 deficiency was found to limit lung adenocarcinoma and LLC cell proliferation in vivo and in vitro." (PMID 40794328, 2025). "Given that loss of PON2 expression was detrimental to lung adenocarcinoma cell proliferation, we sought to investigate the impact of PON2 on cellular bioenergetics through a stable isotope resolved metabolomics (SIRM) approach." (PMID 37337025, 2023). "Taken together, the results of SIRM studies demonstrate that the loss of endogenous PON2 expression impairs key aspects of oxidative metabolism in lung adenocarcinoma cells." (PMID 37337025, 2023). "Contrastingly, RNAi-mediated PON2 knockdown was found to further elevate the rates of apoptosis and imatinib susceptibility while PON2-deficient lung adenocarcinoma cells caused concentration-dependent surges in cell death and activation of caspase-3/7 upon C12 treatment." (PMID 40794328, 2025). "In addition, the loss of endogenous PON2 expression impaired key aspects of oxidative metabolism in lung adenocarcinoma cells." (PMID 37337025, 2023). "Raised PON2 levels in human lung adenocarcinoma cells, particularly altered cell cycle progression and metabolism, revealing a steady decline of PON2 in Lewis Lung Carcinoma cells through RNA interference." (PMID 40794328, 2025). "To overcome these drawbacks, we developed a primary lung adenocarcinoma mouse model to investigate the role of PON2 in pulmonary tumorigenesis." (PMID 37337025, 2023). "As such, one of major conclusions of this study is that elevated PON2 expression serves to promote cellular proliferation in vitro by enhancing lung adenocarcinoma mitochondrial bioenergetics." (PMID 37337025, 2023). "To obtain detailed insight into PON2’s role in oxidative metabolism within lung adenocarcinoma cells, we analyzed the abundances of labeled intracellular metabolites produced from [U-13C]-glucose using two dimensional (2D) TOCSY analysis." (PMID 37337025, 2023). "The Wnt pathway plays a significant role in lung tumors and our previous cell culture experiments demonstrated that lung adenocarcinoma A549 cells, which express high amounts of PON2, went into apoptosis after siRNA-mediated PON2 knock-down." (PMID 27322774, 2016). "Since PON2 expression has been found to increase in human lung adenocarcinoma, we further investigated the role of PON2 in cellular proliferation of two human lung adenocarcinoma cell lines, A549 and NCI-H1299 cells." (PMID 37337025, 2023). "Herein, we have systematically evaluated major aspects of cellular bioenergetics in cultured lung adenocarcinoma cells with or without endogenous PON2 expression." (PMID 37337025, 2023). "In the three lung tumor models examined, PON2 expression in subcutaneously or orthotopically transplanted tumors and primary lung adenocarcinoma driven by oncogenic Kras as well as in host mice failed to significantly impact the initiation and development of tumors." (PMID 37337025, 2023). "PON2 status in both transplanted tumor cells and mice failed to influence the development of subcutaneously grafted Lewis lung carcinoma (LLC) tumors, orthotopically implanted LLC tumors, and oncogenic Kras-driven primary lung adenocarcinoma tumors." (PMID 37337025, 2023).
Nephropathy (3 papers, 2011 to 2023). A nonspecific term referring to disease or damage of the kidneys. "PON2 knockout mice are more susceptible to glomerular damage in models of aggravated oxidative stress such as adriamycin-induced nephropathy." (PMID 36429053, 2022). "Some studies reported associations of PON2 genetic variation with renal dysfunction or nephropathy." (PMID 21223581, 2011). "In in vivo studies, capsazepine reduced the glomerular phenotype in the model of adriamycin-induced nephropathy in PON2 knockout mice and wildtype littermates." (PMID 36672207, 2023). "Capsazepine treatment produced a robust protective effect in PON2 knockout mice in the adriamycin-induced nephropathy model, characterized by a reduction in albuminuria at 14 days." (PMID 36672207, 2023). "The present study suggests that TRPC6 contributes to the deleterious effects of a PON2 knockout in the adriamycin-induced nephropathy mouse model, at least at early stages of the disease." (PMID 36429053, 2022). "Therefore, to promote oxidative stress on cellular membranes, we employed the model of adriamycin-induced nephropathy to PON2 knockout mice as well as to wildtype and heterozygous littermates." (PMID 36429053, 2022).
Parkinson disease (3 papers, 2014 to 2023). A progressive degenerative disorder of the central nervous system characterized by loss of dopamine producing neurons in the substantia nigra and the presence of Lewy bodies in the substantia nigra and locus coeruleus. "In summary, we demonstrate that DJ-1, a Parkinson's disease related gene, interacts with PON2 in neurons and cell lines." (PMID 25210784, 2014). "Besides, the expression of PON2 in DJ-1 KO neurons is more protective against the Parkinson’s model of neuronal death than the expression of DJ-1 in PON2 deficient background." (PMID 33562328, 2021). "In addition, expression of PON2 in DJ-1 KO neurons is more protective against Parkinson's model of neuronal death than expression of DJ-1 in PON2 deficient background." (PMID 25210784, 2014).
allergic asthma (2 papers, 2014 to 2024). A asthma with a basis in a pathological type I hypersensitivity reaction. "On the contrary, the hierarchical cluster analysis of the MDR data in women showed that the CYBA 640A>G, GPX4 C718T, and PON2 S311C gene polymorphisms have a strong synergistic interaction effect on the risk of allergic asthma." (PMID 24895604, 2014). "In this study, we used a transgenic mouse model of non-allergic asthma as well as in vitro cell culture assays to demonstrate that PON2 is an important modulator of airway responses to oxidant stress." (PMID 39594475, 2024). "Using Pon2−/− mice and acute ozone exposure as a model of non-allergic asthma, we show that decreased expression of Pon2 results in more severe AHR." (PMID 39594475, 2024).
breast cancer (2 papers, 2024 to 2025). A primary or metastatic malignant neoplasm involving the breast. "PON2 immunohistochemical expression was also evaluated in several molecular subtypes of breast cancer: luminal A, luminal B, luminal B HER2+, HER2+, and triple-negative breast cancer (TNBC)." (PMID 38397445, 2024).
cervical cancer (2 papers, 2016 to 2025). A primary or metastatic malignant neoplasm involving the cervix. "A significant PON2 overexpression in HeLa cervical cancer cells alleviates the oxidative damage induced by hydrogen peroxide." (PMID 40794328, 2025).
chronic myeloid leukemia (2 papers, 2012 to 2022). "Interestingly, PON2 knockdown enhanced apoptosis-related death of chronic myeloid leukemia K562 cells receiving treatment with Bcr-Abl tyrosine-kinase inhibitor imatinib, while the opposite effect was induced upon enzyme upregulation." (PMID 36613780, 2022).
endothelial dysfunction (2 papers, 2015 to 2019). In vascular diseases, endothelial dysfunction is a systemic pathological state of the endothelium (the inner lining of blood vessels) and can be broadly defined as an imbalance between vasodilating and vasoconstricting substances produced by (or acting on) the endothelium. "13-hydroxy-(9E_11E)-octadecadienoic acid may play a role in antiatherosclerosis by avoiding endothelial dysfunction by regulating the antioxidant effect of PON2." (PMID 26169365, 2015).
glomerular disease (2 papers, 2022 to 2023). "PON2 deficiency reproduces features of an altered lipid composition of glomerular disease, characterized by an increase in ceramides and cholesterol." (PMID 36429053, 2022). "In this study, we employ a genetic deletion of the anti-oxidative, lipid-modifying paraoxonase 2 enzyme (PON2) as a model to study altered cellular lipid composition and its effects on cellular signaling in glomerular disease." (PMID 36429053, 2022). "In the present study, we introduce a model of lipid peroxidation of the cellular membranes induced by abrogating the expression of PON2 in cultured podocytes and in mouse models of glomerular disease." (PMID 36429053, 2022).
hepatocellular carcinoma (2 papers, 2017 to 2025). A malignant tumor that arises from hepatocytes. "In HepG2 hepatoma cells, lead acetate-induced oxidative stress has been associated with reduced PON2 activity, however this could potentially be restored with calcium treatment." (PMID 40794328, 2025). "Till now, upregulated levels of PON2 have been detected in different types of cancer cells, such as hepatocellular carcinoma, prostate cancer and pediatric acute lymphoblastic leukemia, and it has been suggested a possible involvement of PON2 in apoptotic escape of tumor cells." (PMID 28430636, 2017).
HIV-1 infection (2 papers, 2012 to 2025). The type species of lentivirus and the etiologic agent of acquired immunodeficiency syndrome (AIDS). "To determine whether polymorphisms in the PON-1 and PON-2 genes, along with paraoxonase activity, are associated with HIV-1 infection in PLWH, we conducted a sex-matched case-control study." (PMID 40002395, 2025). "Based on the results described, the odds ratio (OR) of the susceptibility to HIV-1 infection in relation to polymorphisms of the PON-1 and PON-2 genes was calculated using univariate binary logistic regression." (PMID 40002395, 2025). "Additionally, it is important to explore the molecular and pathophysiological mechanisms underlying HIV-1 infection and the role of PON-1 and PON-2 polymorphisms, along with their enzyme activities, to reduce oxidative stress in PLWH." (PMID 40002395, 2025).
Lewis Lung Carcinoma (2 papers, 2023 to 2025). "To explore PON2’s role in pulmonary oncogenesis, we first sought to investigate how PON2 may impact cellular proliferation of murine Lewis lung carcinoma (LLC) cells." (PMID 37337025, 2023).
liver fibrosis (2 papers, 2022 to 2024). "Notably, very significant associations for rare and very rare PON2 variants with liver fibrosis were revealed." (PMID 39334710, 2024). "Additionally, rare and very rare variants in PON2 were discovered to be associated with MASLD-related hepatic fibrosis." (PMID 39334710, 2024). "We demonstrated that PON2 depletion is directly associated with the pathogenesis of steatohepatitis and liver fibrosis, as evidenced by the mRNA expression of genes related to the regulation of macrophage activation, collagen metabolism, and other inflammation-related pathways." (PMID 36509805, 2022). "Highly significant results were consistently observed for rare and very rare PON2 variants when comparing samples without liver fibrosis to samples with varying stages of liver fibrosis." (PMID 39334710, 2024). "Finally, we are the first to report an association between rare PON2 variants and MASLD-related liver fibrosis." (PMID 39334710, 2024). "Notably, we are the first to report an association between naturally occurring rare PON2 variants and MASLD-related liver fibrosis." (PMID 39334710, 2024). "Considering the critical role of liver fibrosis in MASLD outcome, PON2 emerges as a possible candidate for future research endeavors including exploration of biomarker potential." (PMID 39334710, 2024). "Thus, we suggest that PON2 deficiency in hepatocytes may cause liver damage, through the increased ceramide synthesis, consequentially leading to severe progression of NAFLD to steatohepatitis and liver fibrosis." (PMID 36509805, 2022). "Given the crucial role of liver fibrosis in clinical MASLD outcome prediction, PON2 might prove a promising target for future research, including exploring its potential as a biomarker or as a possible therapeutic target." (PMID 39334710, 2024). "To the best of our knowledge, we are the first to report that natural genetic variation in PON2 might be meaningful in the etiology and/or progression of MASLD-related liver fibrosis." (PMID 39334710, 2024).
myocardial ischemia (2 papers, 2023 to 2024). A disorder of cardiac function caused by insufficient blood flow to the muscle tissue of the heart. "PON2 can prevent acute myocardial ischemia‐reperfusion injury by regulating mitochondrial function and oxidative stress through the PI3K/Akt/GSK‐3β RISK pathway." (PMID 36840500, 2023). "Moreover, PON2 protects against acute myocardial ischemia‐reperfusion injury by regulating mitochondrial function and oxidative stress through the PI3K/Akt/GSK‐3β RISK pathway." (PMID 36840500, 2023).
non-Hodgkin lymphoma (2 papers, 2012 to 2021). Distinct from Hodgkin lymphoma both morphologically and biologically, non-Hodgkin lymphoma (NHL) is characterized by the absence of Reed-Sternberg cells, can occur at any age, and usually presents as a localized or generalized lymphadenopathy associated with fever and weight loss. "PON2 overexpression was detected in the pancreas, liver, kidney, and lung tumors and an over 10-fold upregulation of PON2 in thymus tumors and non-Hodgkin’s lymphomas." (PMID 33562328, 2021). "We showed a moderate PON2 overexpression in pancreas, liver, kidney, and lung tumors and an over 10-fold upregulation of PON2 in thymus tumors and non-Hodgkins lymphomas." (PMID 22666600, 2012).
oral squamous cell carcinoma (2 papers, 2022 to 2025). "In oral squamous cell carcinomas (OSCC), knocking down PON2 significantly increased the irradiation‐induced apoptosis rates while upregulation of PON2 could protect OSCC against apoptosis." (PMID 35716032, 2022).
pancreatic ductal adenocarcinoma (2 papers, 2020 to 2025). An infiltrating adenocarcinoma that arises from the epithelial cells of the pancreas.
retinal degeneration (2 papers, 2023 to 2026). Degeneration of the retina. "NaIO3 treatment caused significant retinal degeneration, retinal thinning, and reduced rod and cone function in PON2-deficient mice when compared to WT mice." (PMID 37891899, 2023). "In the current study, we demonstrated that compared to WT mice with retinal degeneration, PON2-deficient mice had significantly more TUNEL-positive cells and activated caspase-3." (PMID 37891899, 2023).
Stroke (2 papers, 2006 to 2013). Sudden impairment of blood flow to a part of the brain due to occlusion or rupture of an artery to the brain. "PON2-311 "CC" genotype (SS variant) was higher in male cardioembolic (CE) stroke patients than in male controls (p = 0.03, OR = 2.05)." (PMID 16551349, 2006). "A negative association has previously been demonstrated between SNPs in the coding region of PON1 and PON2, and the development of stroke." (PMID 23356507, 2013).
thyroid cancer (2 papers, 2021 to 2025). "PON2 knockdown partially inhibits the proliferation of thyroid cancer cells produced via miR-376a-3p inhibitors revealing that PON2 has a complex regulatory function in these cells." (PMID 40794328, 2025). "A research study on PON2 knockdown was found to mimic the inhibition of apoptosis in thyroid cancer cells mediated via the miR-376a-3p inhibitor." (PMID 40794328, 2025). "Among these targets, PON2 was considered to be a potential target of miR-376a-3p in thyroid cancer since its critical role in the regulation of tumor progression." (PMID 33600548, 2021). "Last but not least, rescue experiments demonstrated that the essential role of miR-376a-3p-PON2 axis in mediating the effects of LINC00488 on the thyroid cancer cell progression." (PMID 33600548, 2021). "Taken together, lncRNA LINC00488 activated thyroid cancer cell progression by targeting the miR-376a-3p/PON2 axis." (PMID 33600548, 2021). "Mechanistically, LINC00488 served as oncogenic gene in thyroid cancer progression through regulation of miR-376a-3p/PON2 axis." (PMID 33600548, 2021). "Collectively, our findings indicated that LINC00488 might enhance PON2 expression by sequestering the miR-376a-3p in thyroid cancer." (PMID 33600548, 2021). "Rescue experiment indicated that LINC00488 might enhance PON2 expression by sponging miR-376a-3p in thyroid cancer." (PMID 33600548, 2021). "In addition, we validate the mRNA expression levels of PON2 in human normal thyroid cell line Nthy-ori3-1 and human thyroid cancer cell lines (BCPAP, BHP5-16, TPC-1 and CGTH-W3)." (PMID 33600548, 2021). "Therefore, the LINC00488-miR-376a-3p-PON2 axis may serve as novel biomarkers or potential targets for the treatment of thyroid cancer." (PMID 33600548, 2021). "Hence, the main objective of the study was to decipher the roles of LINC00488-miR-376a-3p-PON2 pathways in thyroid cancer, thereby providing a deep understanding of the LINC00488’s function in thyroid cancer to develop it as a promising diagnostic and therapeutic target for this disease." (PMID 33600548, 2021).
vascular dementia (2 papers, 2014 to 2023). A degenerative vascular disorder affecting the brain. "PON2 311Ser, along with another gene, the apoE4 allele, helps in the development of AD and vascular dementia." (PMID 37891899, 2023). "The most top selected SNPs in SMML method in multiclass classifications come from gene “PON2,” which encodes paraoxonase-2 gene and is associated with apolipoprotein E4 allele in both Alzheimer's and vascular dementias." (PMID 25368574, 2014).
acute myocardial infarction (1 paper, 2019). Necrosis of the myocardium, as a result of interruption of the blood supply to the area. "In an animal model, PON-2 protects against acute myocardial infarction by reducing mitochondrial dysfunction and oxidative stress in cardiomyocytes by the PI3K/Akt/GSK-3β pathway." (PMID 31052559, 2019). "The altered relationship between PON-2 and mitochondria can also be observed in acute myocardial infarction (AMI); the lack of oxygen and the increase in ROS production are the main factors for cardiac tissue necrosis." (PMID 31052559, 2019).
airway hyperresponsiveness (1 paper, 2024). "We find that knockout of Pon2 in mice leads to increased airway hyperresponsiveness following O3 exposure." (PMID 39594475, 2024). "We hypothesize that decreased PON2 results in worsened airway hyperresponsiveness, increased airway inflammation, and damaged mitochondria after an exogenous oxidant stressor." (PMID 39594475, 2024).
Arthritis (1 paper, 2020). Inflammation of a joint. "Levels of PON2 and PON3 proteins were significantly higher in livers from PON1KO mice compared to WT controls following arthritis induction." (PMID 33033318, 2020).
B-cell lymphoblastic leukaemia (1 paper, 2025). "A study deployed CRISPR-Cas9 to delete PON2 in B-cell lymphoblastic leukaemia (B-ALL) models, where PON2 loss disrupted cell cycle regulation and delayed cell proliferation and discovered that high PON2 levels had been linked with poor survival in paediatric B-ALL." (PMID 40794328, 2025).
brain tumor (1 paper, 2018). "Our findings demonstrate that the highest level of PON2 expression isobserved in solid tumors, in particular in brain tumor and liver cancer.Amplification of the PON2 gene and correlation of itsexpression with unfavorable prognosis of survival are also typical of thesetumors." (PMID 30397533, 2018).
cataract (1 paper, 2021). Partial or complete opacity of the crystalline lens of one or both eyes that decreases visual acuity and eventually results in blindness. "A combined genotype analysis for PON2 polymorphisms revealed that the combination of G148 and S311 was more frequent in cataract subjects, whereas heterogeneous alleles at 311 and 148 were more likely to be present in subjects without lens opacity." (PMID 33562328, 2021).